SOD1 (superoxide dismutase 1)
Diseases named in the same sentence as SOD1 in open-access papers (continued):
Sharing a sentence is not in itself a finding about the gene and the disease.
motor neuron disease (continued). "Although aggregation of mutant SOD1 is by some manner linked to the toxic property of the protein that is responsible for inducing motor neuron disease, the nature of the toxic property remains incompletely defined and may be multifactorial." (PMID 24341866, 2013). "Notably, this critical difference may represent the major pathogenic shortcomings of the SOD1 mouse model as a tool for studying motor neuron diseases." (PMID 36836867, 2023). "However, it has yet to be established whether a loss of function is the underlying mechanism in SOD1-related motor neuron disease, meaning that the usefulness of SOD targeting as an approach for ALS has yet to be defined." (PMID 33805942, 2021). "In the Phase I trial with familial ALS with SOD1, SOD1 overexpression has a capacity to improve ROS clearance, delay motor neuron disease progression, and improve survival." (PMID 40806624, 2025). "Paradoxically, the motor neuron disease accelerates in rodent models that mimic the co-expression of wild-type SOD1 with mutant fALS SOD1." (PMID 41237982, 2025). "Mouse models have also been developed, expressing multiple copies of the mouse SOD1 mutant with early fatal motor neuron disease." (PMID 36836867, 2023). "Mutations in a number of different genes, including C9ORF72, TDP43, FUS and SOD1, can all lead to some form of motor neuron disorder or the related cognitive disorder frontotemporal dementia." (PMID 37671010, 2023). "Mouse models have also been developed, expressing multiple copies of the SOD1 mutant genes with early fatal motor neuron disease." (PMID 36836867, 2023). "Animals expressing altered SOD1 develop a motor neuron disease resembling human disease, with different periods of manifestation and rates of progression." (PMID 36836867, 2023). "Transgenic mice expressing human SOD1G93A develop a rapidly progressive motor neuron disease similar to fALS52, despite expression of endogenous mouse wild-type SOD1 (SOD1WT), with only a minor effect on the enzymatic activity of SOD1." (PMID 35688953, 2022). "Remarkably, inoculation of SOD1 aggregates, prepared from spinal cords of transgenic mice as well as humans carrying mutant SOD1s, was recently shown to transmit both SOD1 aggregation and fatal motor neuron disease to transgenic mice." (PMID 35406813, 2022). "SOD1 is involved in the pathogenesis of the motor neuron disease ALS where it is observed to form intracellular fibrillar inclusions." (PMID 35715417, 2022). "Overall, the data show that WT-SOD1 is relatively resistant to prion-like seeding towards induction of motor neuron disease or the type of inclusion pathology present in mice expressing fALS mutant SOD1." (PMID 34016165, 2021). "By motor score and PaGE test analysis, the first clinical signs of motor neuron disease in SOD1-G93A were observed from week 12 (disease onset) with hind limb tremors and reduced muscular strength." (PMID 34356873, 2021). "The present study describes a broader analysis of seeding across a larger panel of SOD1 variants to characterize the influence of primary sequence on the efficacy of seeding to induce motor neuron disease in SOD1 transgenic mice." (PMID 34016165, 2021). "Overall, there is considerable evidence that the misfolding and aggregation of mutant SOD1 is a key event in the toxic processes that produce motor neuron disease." (PMID 31999698, 2020). "SOD1 transgenic animals that express human mutant SOD1 develop progressive motor neuron disease and represent a very good model for the human disease." (PMID 33244084, 2020). "In previous studies, we have demonstrated the ability to induce motor neuron disease (MND) in mice that express G85R-SOD1: YFP at low levels by injecting recombinant WT SOD1 that had been fibrilized in vitro." (PMID 31999698, 2020). "While 1000x Ω-3 suppressed inflammation in SOD-1 mice, it unexpectedly hastened the progression of motor neuron disease." (PMID 29387280, 2017).
motor neuron disease (continued). "As shown herein, supplementation of SOD-1 mice with Ω-3 along with similar or increased levels of Ω-6 delayed the progression of motor neuron disease." (PMID 29387280, 2017). "On the other hand, SOD1 transgenic mice with additional depletion of the Rag2 gene (mSOD1/RAG2−/− mice) show delayed motor neuron disease, thus suggesting that mature lymphocytes produce deleterious effects on vulnerable motor neurons." (PMID 29081763, 2017). "We conclude that Stathmin-triggered microtubule destabilization mediates Golgi fragmentation in mutant SOD1-linked ALS and potentially also in related motor neuron diseases." (PMID 27277231, 2016). "Genetic modulation of the UPR in transgenic mice over-expressing mutant human SOD1 significantly influences motor neuron disease symptom onset and lifespan." (PMID 26288094, 2015). "At 8 months abnormal reflexes were detected, characterized by retraction of hind limbs, as seen in the G93A SOD1 mouse model of motor neuron disease, which was accompanied by a reduction in motor neuron number of 24% in DAO−/− mice." (PMID 24795623, 2014). "The T70I sod1 zebrafish demonstrates key features of ALS: an early NMJ phenotype, susceptibility to oxidative stress and an adult-onset motor neuron disease phenotype." (PMID 24092880, 2014). "Apart from key ataxia proteins like ataxin-1 or ataxin-3, this degradation also includes proteins involved in motor neuron disease such as SOD1 proteins." (PMID 24742043, 2014). "The gene expression changes observed in the gastrocnemius muscle of SOD1-G93A transgenic mice suggest that neuromuscular impairments precede motor neuron death at pre-symptomatic periods of motor neuron disease." (PMID 24895011, 2014). "ALS transgenic models including mutant SOD1 transgenic mice but more recently including other transgenic constructs have provided powerful tools for exploring the basic biology of motor neuron disease and testing experimental therapeutics." (PMID 22830014, 2012). "Among the catalogued ALS-like motor neuron diseases, mutations in SOD1 (ALS1), FUS/TLS (ALS6), VAPB (ALS8), ANG (ALS9), TARDBP (ALS10), FIG4 (ALS11) and a hexanucleotide-repeat expansion (GGGGCC) in the C9ORF72 cause adult onset neurodegenerative disorder." (PMID 22384259, 2012). "Mouse model of motor neuron disease (SOD1-G93A) was injected intramuscularly with Brain-derived neurotrophic factor (BDNF-TTC) encoding or control naked DNA plasmids." (PMID 21044297, 2010). "In order to learn more about the role of microglia in the pathogenesis of motor neuron disease, we set out to investigate microglial activation in the G93A SOD1 mutant rat during natural disease progression." (PMID 17328801, 2007). "We developed a mouse model of ALS using NSG mice expressing G93A human SOD1 that develops ALS-like motor neuron disease with spinal cord neuroinflammation while permitting long-term survival of human cells due to the absence of a murine adaptive immune response." (PMID 40940730, 2025). "Corroborating that the phenotype is caused by the patient being homozygous for D90A SOD1, transgenic mice overexpressing D90A mutant human SOD1 develop a slowly evolving motor neuron disorder beginning in the hind legs and also involving bladder disturbance with incontinence." (PMID 36385230, 2023). "Thus, to achieve at least 50% target reduction with minimal toxicity, we proceeded with two independent Atp1a2 targeting ASOs, ASO1 at 50μg and ASO3 at 25μg, to characterize effects of Atp1a2 knockdown in motor neuron disease in SOD1*G93A animals." (PMID 38015828, 2023). "Though it is not surprising that elimination of neuronal expression of G85R-SOD1:YFP would inhibit induction of motor neuron disease in this model, the data provide a confirmation of the role of neurons in propagating misfolded SOD1 ALS conformers that induce paralysis." (PMID 37766226, 2023).
motor neuron disease (continued). "Sigma-1 agonists, which activate TrkB receptors, have been shown to increase BDNF levels in the rat hippocampus and demonstrate neuroprotective effects in a non-SOD1 motor neuron disease model, Huntington's disease model, and an SOD1 ALS model through the ERK and Akt pathways downstream of TrkB." (PMID 35283994, 2022). "The identification of genetic modifiers of motor neuron disease, especially those modifiers that are shared by SOD1 and dynactin-1 transgenic mice, may help to develop biomarkers predictive of disease progression." (PMID 36107978, 2022). "Essentially, gene mutations in SOD1 lead to sharp reductions in SOD activity levels, which in turn results in increased levels of ROS that give rise to the progressive atrophy and paralysis seen in motor neuron diseases (i.e., ALS)." (PMID 34686594, 2021). "The collective data of the present study and prior work clearly show that spinal cords of paralyzed mutant SOD1 mice contain seed-competent forms of misfolded SOD1 that can induce a self-propagating process, leading to accelerated motor neuron disease and inclusion pathology." (PMID 34016165, 2021). "Moreover, mice that highly over-express WT human SOD1 develop motor neuron disease that is similar to mice expressing mutant SOD1." (PMID 31999698, 2020). "However, more recent studies performed on SOD1 mice showed that neither PERK haploinsufficiency, nor genetic UPR enhancement via ablation of GADD34, is beneficial for mutant SOD1-induced motor neuron disease." (PMID 32854418, 2020). "Downregulation of PRDX3 has been detected in the presence of mutant SOD1G93A motor neuronal-like NSC34 cells, in the spinal cord mitochondria of mutant SOD1 transgenic mice, but also in spinal motor neurons from patients with both sporadic and SOD1-related motor neuron disease (MND)." (PMID 33265993, 2020). "SOD1 rodent lines generally develop adult-onset motor neuron disease, reminiscent of the human disease with hallmarks of human disease such as SOD1 aggregation, excitotoxic cell death of neurons, neuroinflammatory reactions and altered oligodendrocyte biology replicated in SOD1 mouse models." (PMID 31866818, 2019). "Enhanced motor neuron purity could enable investigation of cell-autonomous factors that have been shown to be important for the degenerative mechanisms of other motor neuron disease-related proteins such as superoxide dismutase-1 (SOD1)." (PMID 30190267, 2018). "While this mouse model does recapitulate many features of ALS, mice do not spontaneously develop motor neuron disease when endogenous SOD1 is mutated." (PMID 30295421, 2018). "In this line, altered mitochondria, protein degradation and axonal transport predominate in the 129Sv-SOD1(G93A) transgenic mouse with rapidly progressive motor neuron disease, whereas increased immune response is found in the C57-SOD1(G93A) transgenic mouse with more benign course." (PMID 28283675, 2017). "However, at the end stage (155–175 days of age), hind limb extension was impaired in both SOD1 TG/IL-6(-/-) mice and SOD1 TG/IL-6(+/+) mice, suggesting the motor neuron disease progressed similarly in these mutant mice." (PMID 27070121, 2016). "In conclusion, our data suggest that IL-6 is not a key factor in motor neuron disease caused by SOD1 mutation." (PMID 27070121, 2016). "Loss of NRG1 puncta at C-boutons of motor neurons in both sporadic ALS patients and two distinct lines of SOD1-ALS mice prompted us to test whether NRG1 has a neuroprotective potential for motor neuron disease." (PMID 26891847, 2016). "In conclusion, we have found, somewhat surprisingly, that several of the disturbances associated with SOD1-provoked motor neuron disease including mitochondrial dysfunction and ER stress do not increase SOD1 misfolding or aggregation per se." (PMID 26919046, 2016).
motor neuron disease (continued). "Selective expression of OPN in ALS-resistant FR/S MNs and ECM accumulation in both the FALS case and three lines of SOD1-ALS model mice prompted us to test whether OPN is neuroprotective against motor neuron disease." (PMID 27264390, 2016). "Selective expression of mutant SOD1 only in astroglia, causes a type of astrogliosis but fails to produce motor neuron disease in the absence of simultaneous mutant SOD1 expression in neurons." (PMID 16436205, 2006). "Since PD, HD, and ALS share aspects of pathogenesis and pathology of motor dysfunction, we also studied gait dynamics in the SOD1 G93A transgenic mouse model of ALS to compare gait variability in mouse models of basal ganglia disease to a mouse model of motor neuron disease." (PMID 16042805, 2005). "Importantly, the development of motor neuron disease is not due to a loss of SOD1 function, as many mutant forms of SOD1 retain nearly normal or even elevated SOD1 activity." (PMID 40940747, 2025). "Thus, while neither upregulated expression of wild-type SOD1 nor obliteration of endogenous SOD1 caused motor neuron disease, it is evident that the disease is induced by an acquired toxicity of mutant SOD1 independent of its dismutase activity." (PMID 40940747, 2025). "Transgenic mice overexpressing human mutant SOD1 have been shown to develop ALS-like symptoms, but not in mice knockout or overexpressing wild-type SOD1 genes, indicating that mutant SOD1 causes motor neuron disease by gaining toxic function rather than by losing normal physiological function." (PMID 38037913, 2024). "The identification of genetic modifiers of motor neuron disease, especially those modifiers that are shared by SOD1 and dynactin-1 transgenic mice, may result in the identification of novel targets for therapies that can alter the course of this devastating illness." (PMID 36107978, 2022). "ALS is the most common form of motor neuron disease, with about 90% of all ALS cases being sporadic, while the other 10% are familial, and about 15–20% of all familial cases are caused by a mutation in the superoxide dismutase-1 glycine 93 to alanine gene (SOD1 G93A)." (PMID 35162978, 2022). "Finally, SOD1-G37R mice also develop a progressive motor neuron disease." (PMID 33921446, 2021). "Moreover, mouse data demonstrate that mutant SOD1 expression causes motor neuron disease, whereas genetic deletion of SOD1 does not." (PMID 29342921, 2018). "Moreover, injection of spinal cord homogenates from mice overexpressing wild-type or mutant SOD1 into naïve animal heterozygous YFP-SOD1G85R led to transmission of motor neuron disease and interestingly, different abundances and localizations of SOD1 inclusions and fibrils." (PMID 27121871, 2016). "Recent work provides striking evidence that this may indeed drive disease progression as focal injection of spinal cord homogenates from symptomatic G93A SOD1 triggers progressive motor neuron disease in mice expressing G85R SOD1-YFP below the threshold for disease." (PMID 26520394, 2015). "A similar effect was observed by Gowing and coll: genetic ablation of TNFα (TNFα gene knock out) does not affect motor neuron disease caused by SOD1 mutations, although higher level of TNFα and of its soluble receptors have been shown in plasma from ALS patients." (PMID 21445241, 2011). "The observation that transplanted wild-type muscles do not inhibit the occurrence of muscle denervation in B6.SOD1 mice provides increased confidence that expression of the G93A SOD1 mutation in muscle is not necessary for the appearance of muscle denervation or the motor neuron disease phenotype." (PMID 20339550, 2010). "Selective Cre-mediated gene excision of mutant SOD1 in astrocytes improved the survival of SOD1 expressing mice, while mutant SOD1 expression in cell types other than motor neurons and oligodendrocytes seem to accelerate the onset of motor neuron disease phenotype." (PMID 19165334, 2009).
motor neuron disease (continued). "In addition, in vivo experiments show that SOD1-D91A (p.Asp91Ala), the most common mutation affecting SOD1 linked to ALS, is less toxic than other tested mutants, while homozygous mice develop fatal motor neuron disease similar to that observed in homozygous-D91A human ALS patients." (PMID 35328090, 2022). "However, according to the recent studies using SOD1 TG mice lacking lymphocytes, the adaptive immune system is not pathogenic in motor neuron disease, but rather may be protective against the disease progression." (PMID 27070121, 2016). "Transgenic expression of mSOD1 in mice (G93A-SOD1 mice) triggers motor neuron disease closely resembling human ALS, despite normal levels of endogenous SOD1." (PMID 23776455, 2013). "Our results uncouple SOD1 aggregation and disease course and show that downregulation of Atp1a2 by ASOs before disease onset fails to slow motor neuron disease in mutant SOD1 mice." (PMID 38015828, 2023). "Analogous to our findings, astrocyte-targeted expression of mutant SOD1 is not sufficient to trigger onset of motor neuron disease in mice." (PMID 37075107, 2023). "The ALS-SOD1 pathogenesis was initially believed to arise from the oxidative damage caused by reduced SOD1 activity, nevertheless, studies have further revealed that SOD1-null mice do not develop motor neuron disorder." (PMID 33630959, 2021). "We performed extensive immunopathological analyses using mutant superoxide dismutase 1 (SOD1G93A) transgenic mice and their littermates to investigate whether Cx36-made electrical synapses are affected in motor neuron diseases." (PMID 30546295, 2018). "Intriguingly, loss of Ccs did not affect the time of onset or progression of motor neuron disease in Sod1 mutants, whereas in contrast, over-expression of Ccs in a Sod1-mutant background strongly accelerated neurological disease." (PMID 25253562, 2014). "On the other hand, SOD1 mutants induce motor neuron disease independent of copper incorporation into SOD1 mutants mediated by copper chaperone for SOD1 (CCS), and copper-binding-site-null SOD1 still causes ALS in transgenic mice." (PMID 23755211, 2013). "First, transgenic expression of mutant SOD1 restricted to neurons using a neurofilament light-chain promoter fails to produce motor neuron disease." (PMID 22830014, 2012). "Gait variability was not significantly higher in SOD1 G93A mice, a model of motor neuron disease, compared to wild-type control mice." (PMID 16042805, 2005). "To determine whether PC death is a shared feature of motor neuron diseases, we investigated the cerebellum of milder Smn2B/- SMA mice as well as SOD1-G93A and Ighmbp2NMD-2J mice as models of familial ALS and SMA with respiratory distress type 1 (SMARD1), respectively." (PMID 40585211, 2025). "Interestingly, a complete loss of SOD1 enzymatic activity does not lead to ALS but to a severe, progressive, infantile-onset motor neuron disease in humans, presumably due to a perturbation of the signaling function of superoxide/H2O2." (PMID 35406813, 2022). "In addition, there is a considerable amount of evidence demonstrating that GLP-1RAs reduce brain damage in animal models of ischaemic stroke and traumatic brain injury, and improve the survival of motor neurons in the mutant superoxide dismutase 1 (SOD1; G93A) model of motor neuron disease." (PMID 35805109, 2022). "While inoculation of minute amounts of SOD1 aggregates with prion-like properties into the CNS readily induces spreading aggregation and premature fatal motor neuron disease, peripheral administration of large amounts did not induce disease in the hSOD1 Tg mice." (PMID 34158126, 2021). "Taking into account reports on abnormal accumulation of misfolded SOD1 in PD brains and also of α-synuclein in ALS spinal cords, there would be a shared pathomechanism between ALS and PD; indeed, sporadic and familial cases of motor neuron disease with parkinsonism have been occasionally reported." (PMID 31744522, 2019).